CLOCK (clock circadian regulator)
Diseases named in the same sentence as CLOCK in open-access papers (continued):
Sharing a sentence is not in itself a finding about the gene and the disease.
glioma (continued). "For brain tumors, the expression of CLOCK in high-grade glioma cells increases significantly compared with low-grade gliomas and non-gliomas, likely due to a decrease in miR-124 expression, which regulates RNA expression." (PMID 34966277, 2021). "Expression of CLOCK is significantly higher in high-grade gliomas relative to low-grade gliomas or normal brain." (PMID 33302582, 2020). "Mechanistically, results illustrated that restoration of miR-124 or silencing of CLOCK in glioma cell decreased the nuclear factor kappa B (NF-κB) activity, which suggested a potential miR-124/CLOCK/NF-κB axial relationship in gliomagenesis." (PMID 32195174, 2020). "In coherence with previous reports, the glioma stimulating effect of the core circadian gene, CLOCK was emphasized." (PMID 32195174, 2020). "CLOCK expression is significantly increased in patient samples of gliomas relative to the surrounding tissue." (PMID 33302582, 2020). "Downregulation of the circadian genes encoding CRY2, PER1, PER2, PER3, CLOCK, REV-ERBβ, ROR-α and ROR-β was associated with significantly higher mortality rates in the glioma cohort, hinting at possible tumor suppressor roles." (PMID 32631383, 2020). "This study will discuss the expression of UCA1 regarding miR-206 and CLOCK, and their integrative effects in the proliferation and cell cycle of glioma cells." (PMID 31798345, 2019). "The axis of UCA1/miR-206/CLOCK was a valid prognostic indicator and a new therapeutic method for glioma." (PMID 31798345, 2019). "Our experiments, results, and analysis indicated that UCA1 enhanced cell growth and invasion through the miR-206/CLOCK axis in glioma." (PMID 31798345, 2019). "CLOCK expression is increased in high-grade glioma tissues and is required for glioma progression through modulation of NF-κB activity." (PMID 31014368, 2019). "This study will discuss the expression of UCA1 regarding miR-206 and CLOCK, and their integrative effects on the progressing and cell cycle of glioma." (PMID 31798345, 2019). "To our best knowledge, we are the first to propose that the axis of UCA1/miR-20/CLOCK plays a critical role in the regulation of glioma development." (PMID 31798345, 2019). "It has been shown that CLOCK was found to be significantly increased in gliomas and colorectal carcinoma." (PMID 28058089, 2016). "Previous reports link GSC CLOCK/BMAL1 signaling to glioma immunosuppression." (PMID 41480765, 2026). "Major mutated CRGs in LGG are PER2, BMAL1, CLOCK and BMAL2, which might indicate these genes are most influencial CRGs to glioma development or metastasis." (PMID 39043735, 2024). "M2 phenotype microglia can promote glioma proliferation and migration by delivering miRNA-7239-3p to glioma cells via exosomes, regulating their tumor-associated protein expression (BMAL1 down-regulation, CLOCK up-regulation) and reducing tumor cell apoptosis." (PMID 37700840, 2023). "Interestingly, another study of in vitro glioma cells demonstrated that IDH1 mutations are associated with lower expression of BMAL1, CLOCK, PER genes, and CRY genes compared to their wildtype counterparts." (PMID 38173841, 2023). "Scientific data suggest the tumor-progressing role of CLOCK gene in gliomas, indicating that CLOCK could stimulate the proliferation and migration of glioma cells through the inflammatory NF-κB signaling pathway." (PMID 36556190, 2022). "Interestingly, two key CLOCK genes act as oncogenes in glioma; particularly, genes are essential for the survival and proliferation GSCs in vitro." (PMID 36556190, 2022). "Taking into consideration this proof, targeting the circadian clock by altering the CLOCK function could be a promising strategy for glioma and GBM treatment." (PMID 36556190, 2022). "Considering this evidence, targeting the circadian clock by regulating the CLOCK could be a promising approach to treat glioma." (PMID 36556190, 2022). "Recent studies have suggested that CLOCK has a tumor-promoting function in gliomas." (PMID 36556190, 2022).
glioma (continued). "Remarkably, CLOCK might promote the proliferation and migration of glioma cells through the NF-kB signaling pathway." (PMID 34361055, 2021). "More evidence suggests that CLOCK has a tumor-promoting function in gliomas." (PMID 34361055, 2021). "The observed up-regulation of CLOCK might be a consequence of down-regulated miR-124 in glioma which was frequently reported to inhibit tumor cell proliferation and migration through targeting specific genes like Slug, Twist, and Snai2." (PMID 32195174, 2020). "After characterizing the roles of UCA1, miR-206, CLOCK in glioma cells and tissues in vitro, we hope to know whether UCA1 may pose an effect on the glioma growth in vivo." (PMID 31798345, 2019). "The results demonstrated that the axis of UCA1/miR-206/CLOCK could modulate the cell proliferation of glioma cells and the growth of glioma tumors." (PMID 31798345, 2019). "In addition, the in vivo tumor growth shows that UCA1 knockdown repressed glioma growth in vivo, but CLOCK expression was suppressed in tumor tissues." (PMID 31798345, 2019). "Overall, the results demonstrated that UCA1/miR-206/CLOCK axis participated in the progressing of glioma and could act as a promising therapeutic target." (PMID 31798345, 2019). "In particular elevated levels of CLOCK contribute to cell proliferation and migration in glioma." (PMID 24932636, 2014). "Interestingly, CLOCK promotes microglia infiltration in gliomas." (PMID 36556190, 2022). "Notably, CLOCK might increase the proliferation and migration of glioma cells through the NF-κB signaling pathway." (PMID 36556190, 2022). "In addition, evidence in the literature showed that the expression of specific genes related to EMT like Slug, Twist, and Snai2 are involved in the mechanism by which miR-124 inhibits tumor cell proliferation and migration in gliomas and is related to the expression of CLOCK." (PMID 34361055, 2021). "Similarly, CLOCK gene was repeatedly found to have tumor promoting action in glioma cells." (PMID 32195174, 2020). "On one hand, glioma programs e.g. regulated epigenetically by SETD2, SOX10, CLOCK and KDM6 instruct GAM landscapes." (PMID 40642066, 2025). "While BMAL1 and CLOCK are vital for GSC survival, PER1, PER2, and PER3 are downregulated in high-grade gliomas." (PMID 39413708, 2024). "Building upon prior findings, the CLOCK/BMAL1 complex was observed to induce the expression of TBK1 in endothelial cells by secreting POSTN, thereby facilitating glioma TME angiogenesis." (PMID 38607733, 2024). "In glioblastoma, CLOCK and its heterodimeric chaperone BMAL1 behave as tumor-promoting factors, directly modulating the NF-κB pathway, thereby regulating glioma cell migration and proliferation, and maintaining GSC stemness." (PMID 37700840, 2023). "Experimental downregulation of CLOCK and BMAL1 in glioma stem cells (GSCs) results in cell cycle arrest and apoptosis, suggesting that this circadian deregulation is crucial to the growth of GSCs." (PMID 38173841, 2023). "Overall, by increasing the expression of immunosuppressive microglia in the TME, CLOCK and BMAL1 genes can effectively minimize the response of glioma to immunotherapies." (PMID 38173841, 2023). "The expression of the CLOCK gene is augmented in ~5% of GBM patients and high-grade gliomas compared to low-grade gliomas or control." (PMID 36556190, 2022). "In this review, we aimed to highlight the significant modulation of CLOCK, BMLA1 and NOTCH genes in glioma onset and development, praising these genes to be good as potentially attractive therapeutic markers for brain tumors." (PMID 36556190, 2022). "We found that distinctive phenotypes of microglial cells regulate the expression of circadian genes in gliomas: after co-culture with M2 microglia, the expression of BMAL1 protein decreases, while CLOCK expression increases." (PMID 33528793, 2021).
glioma (continued). "Bioinformatic analysis and the experimental validation performed in glioma, a lethal malignant brain tumor, showed that lncRNA UCA1 regulate CLOCK genes via miR-206." (PMID 32344623, 2020). "The growth of glioma tumors was suppressed by the silencing of UCA1 in vivo, and the expression of CLOCK protein was also significantly lowered by the knockdown of UCA1." (PMID 31798345, 2019). "Expression of CLOCK, on the other hand, is found to be upregulated in high-grade glioma compared to low-grade glioma and non-cancerous cells." (PMID 38173841, 2023). "Our results showed that in gliomas co-cultured with M2 microglia, the expression of the BMAL1 protein was decreased (P < 0.01), while the expression of the CLOCK protein was increased (P < 0.05); opposite results were obtained in gliomas co-cultured with M1 microglia." (PMID 33528793, 2021). "CLOCK and its binding partner, BMAL1, are thought to contribute to glioma proliferation, migration, stemness and metabolic reprogramming and a recent paper proposed that GSCs use BMAL1 and CLOCK to alter these characteristics and gain a physiological advantage." (PMID 32631383, 2020). "Unlike control glioma cell line, apoptosis, and cell cycle arrest were increased upon silencing of CLOCK expression of in glioma cell line (U87)." (PMID 32195174, 2020). "CLOCK mRNA expression was significantly decreased in glioma cells transfected with miR-206 mimics and LV-shUCA1 while it was increased in LV-UCA1 transfected glioma cells (p < 0.01)." (PMID 31798345, 2019). "In addition to promote the growth of stem cells in glioma, the BMAL1/CLOCK complex could also recruit immunosuppressive microglia to the TME, thereby establishing conditions associated with poorer prognoses." (PMID 38607733, 2024). "As it was reported for its binding partner BMAL1, TCGA database analysis revealed that the Clock gene, located at 4q12 chromosomal region, is amplified in ~5% of GBM patients, and high-grade gliomas exhibited an increased expression of CLOCK compared to low-grade glioma or non-tumor cells." (PMID 34361055, 2021). "However, the roles of CLOCK in the generation and progression of gliomas are not well understood." (PMID 39001398, 2024). "We confirmed a significant modulation of CLOCK, BMLA1 and NOTCH genes in glioma, particularly praising NOTCH genes family to be good as potentially attractive therapeutic targets for glioblastoma, strengthening the protective role observed in clinical trials for brain tumors." (PMID 36556190, 2022). "This evidence indicated that the expression of CLOCK was closely related to miR-206 and UCA1, which may pose a negative effect on the development of glioma." (PMID 31798345, 2019).
metabolic syndrome (31 papers, 2009 to 2025). A cluster of metabolic risk factors for CARDIOVASCULAR DISEASES and TYPE 2 DIABETES MELLITUS. "Polymorphisms in CLOCK and other core circadian genes have been associated with metabolic syndrome, a condition strongly associated with acne pathogenesis." (PMID 40705802, 2025). "CLOCK genetic polymorphisms have been associated with metabolic syndrome, and one of the most studied CLOCK gene polymorphisms at the 3′-untranslated region is rs1801260." (PMID 34068889, 2021). "The objective of this study was to investigate the association between CLOCK rs1801260 and the incidence of metabolic syndrome modulated by dietary monounsaturated fatty acid (MUFA) intake in Korean adults." (PMID 34068889, 2021). "We analyzed the modulation of the CLOCK rs1801260 polymorphisms and the incidence of metabolic syndrome stratified by dietary MUFA intake." (PMID 34068889, 2021). "A large body of evidence suggests that genetic variation in CLOCK is associated with the development of metabolic syndrome and its components." (PMID 34068889, 2021). "Second, the study utilized a prospective cohort study design to examine the cause–effect relationship of CLOCK polymorphisms and the incidence of metabolic syndrome modulated by dietary MUFA intake." (PMID 34068889, 2021). "Future studies are warranted to elucidate the potential role of sex on the association CLOCK gene polymorphisms and the incidence of metabolic syndrome." (PMID 34068889, 2021). "By dichotomizing dietary MUFA intake, we observed that men who were minor allele carriers (G allele) of CLOCK rs1801260 had a 42% increased incidence of metabolic syndrome when dietary MUFA intake was ≤3.5% (HR: 1.42, 95% CI 1.23–1.81; p Value = 0.004)." (PMID 34068889, 2021). "In this prospective cohort study, we observed an association between the minor allele carriers of the G allele (AG + GG) of CLOCK rs1801260 and the incidence of metabolic syndrome in Korean men." (PMID 34068889, 2021). "In humans, CLOCK gene SNPs are connected to body weight, metabolic syndrome risk, and insomnia, while PER2 and PER3 gene SNPs are linked to sleep disturbances." (PMID 32050674, 2020). "CLOCK is a major circadian regulator: in mice, its mutation disrupts the circadian rhythms and induces a metabolic syndrome." (PMID 26925174, 2016). "In a Korean population study, which used the same cohort data as our research but utilized a different genotype array chip, CLOCK rs1801260 affected the incidence of metabolic syndrome, and the association was more apparent after the stratification of monounsaturated fatty acid intake." (PMID 35276838, 2022). "CLOCK polymorphisms affected metabolic syndrome, modulated by dietary MUFA intake in men." (PMID 34068889, 2021). "However, studies evaluating how CLOCK genetic polymorphisms predispose an individual to metabolic syndrome, and how this relationship is modulated by MUFA, are lacking." (PMID 34068889, 2021). "We hypothesized that CLOCK genetic polymorphisms are associated with the incidence of metabolic syndrome modulated by dietary MUFA intake." (PMID 34068889, 2021). "Additionally, we assessed the association of CLOCK SNP rs1801260 with the incidence of metabolic syndrome modulated by MUFA intake." (PMID 34068889, 2021). "Mutations in CLOCK genes may be a causal factor for the expression of metabolic syndrome components by altering transcriptional regulation, with CLOCK mutant mice showing impaired glucose tolerance." (PMID 34068889, 2021). "Thus, the primary objective of this study was to investigate the association between the common CLOCK SNP rs1801260 and the incidence of metabolic syndrome in Korean adults." (PMID 34068889, 2021). "Specific CLOCK gene polymorphisms are linked to excess weight, metabolic syndrome, and CVD." (PMID 32050674, 2020).
metabolic syndrome (continued). "Delayed breakfast timing disrupts peripheral circadian rhythms and modulates the expression of core clock genes involved in lipid metabolism (including CLOCK and BMAL1), potentially increasing the risk of dyslipidemia." (PMID 41404108, 2025). "In particular, the polymorphisms in CLOCK and BMAL1 genes were reported to be significantly related to cardiovascular disease, metabolic syndrome, sleep reduction, and evening preference." (PMID 38612648, 2024). "In conclusion, we found an association between the presence of the minor alleles (AG + GG) of CLOCK rs1801260 and low dietary MUFA intake with the incidence of metabolic syndrome in Korean men." (PMID 34068889, 2021). "Human research has recognized polymorphisms and transcription motifs of circadian rhythm genes, such as CRY2, CLOCK, ARNTL, PER2, or NPAS2, which are linked with hypertension, metabolic syndrome, or T2DM." (PMID 32050674, 2020). "Studies have shown that CLOCK mutant mice present altered feeding patterns, increased body weight and develop metabolic syndrome accompanied by alterations in lipid and glucose metabolism." (PMID 28645331, 2017). "Supporting evidence comes from CLOCK mutant mice, shown to be hyperphagic and obese and to develop metabolic syndrome in addition to having a disrupted circadian rhythm." (PMID 19203388, 2009). "Indeed, polymorphisms in CLOCK and BMAL1 were associated with the development of metabolic syndrome." (PMID 36676985, 2022). "Research investigating the relationship between CLOCK single nucleotide polymorphisms (SNPs) and the incidence of metabolic syndrome modulated by MUFA intake using a prospective cohort study design is limited, and the role of CLOCK SNPs in metabolic syndrome in Korean adults is unclear." (PMID 34068889, 2021). "Men who were minor allele carriers (G allele) of CLOCK rs1801260 had a 18% higher incidence of metabolic syndrome than non-carriers [hazard ratio (HR), 1.18; 95% confidence interval (CI), 1.00–1.40; p Value = 0.047]." (PMID 34068889, 2021). "Thus, metabolic syndrome, T2DM, and stroke are associated with CLOCK gene variants, while myocardial infarction is associated with CRY2 and PER2 gene variations." (PMID 32050674, 2020). "CLOCK and BMAL1 play a role in protecting the body against symptoms of metabolic syndrome." (PMID 32344535, 2020).